BRAF (B-Raf proto-oncogene, serine/threonine kinase)
Diseases named in the same sentence as BRAF in open-access papers (continued):
Sharing a sentence is not in itself a finding about the gene and the disease.
tumor (continued). "This mutation leads to a conformational change in the BRAF protein, over-activating the downstream kinases MEK1/2-ERK1/2, which in turn activates a series of genes related to cell proliferation and enhanced metabolism, and promotes tumor growth and metastasis." (PMID 36091815, 2022). "Both tumours harbouring 3′ BRAF duplication were cortical lesions in infants (1 and 2 years old)." (PMID 35836307, 2022). "To examine the association of the signature with the clinicopathological characteristics of CRC, we determined the correlation between the signature and different clinical characteristics of CRC (age, sex, tumor location, TNM stage, KRAS mutation, and BRAF mutation)." (PMID 35350786, 2022). "Not only may BRAF inhibitors be ineffective against BRAF fusion driven malignancies, but tumor progression and/or BRAF inhibitor resistance may be promoted." (PMID 35436952, 2022). "Additionally, several studies using paraffin-embedded tumor samples and detection technologies less sensitive than ddPCR reported the concomitant presence of KRAS and BRAF mutations, but in a lower percentage (below 4%) than that found in our study." (PMID 35681771, 2022). "There are major challenges with intrinsic and acquired resistance to BRAF inhibitors, and use of BRAF inhibitors may cause paradoxical activation of the MAPK pathway, leading to increased tumour growth." (PMID 36084109, 2022). "Among the 17 studies, 13 (76.5%) used FFPE tumor samples for KRAS, NRAS and BRAF mutation analysis." (PMID 36344948, 2022). "As the MAPK and PI3K–Akt pathways may positively or negatively regulate mutual activities, the combination of BRAF or MEK inhibitors with a PI3K–Akt inhibitor was proposed to overcome the resistance to MAPK inhibitors in BRAF V600E mutant tumours." (PMID 35335966, 2022). "We further demonstrated that larger tumor size (>1 cm), extrathyroidal extension (ETE), and lateral lymph node metastasis (LNM) were associated with a higher probability of PTC recurrence in patients harboring the BRAF V600E mutation." (PMID 35755312, 2022). "The BRAF-mutated pathway consists of valine replacement with glutamic acid in the BRAF gene at location 600 of the polypeptide chain, transforming it in an active kinase, which is responsible for tumour resistance due to reactivation of the mitogen-activated protein kinase (MAPK) pathway." (PMID 35334544, 2022). "Notably, the in vivointravenous administration of antisense oligonucleotide targeting SAMMSON impairs tumor growth and enhances the pro-apoptotic effect of BRAF inhibitors." (PMID 35912100, 2022). "In addition, using BRAF V600E IHC and/or BRAF molecular analysis, we found that the three tumours with dMMR (MLH1 & PMS2) were BRAF wild-type." (PMID 35768447, 2022). "The discrepancies among the studies on the expression of let-7 miRNAs in CRC could be due to the different characteristics of tumoral tissues in terms of the grade, stage, tumor locations, presence of perineural invasion, and KRAS or BRAF mutation status." (PMID 36295073, 2022). "Many studies have demonstrated that TIME-related genes can interfere with or predict tumor prognosis, but to date, no single prognostic gene or multigene prognostic model for BRAF-mutated PTC has been reported." (PMID 35757399, 2022). "Besides, immune checkpoint inhibitors (ICIs) would be another option since BRAF activation would be a positive biomarker of tumor response of ICIs therapy." (PMID 35912223, 2022). "BRAF mutation was present in 25% and KRAS mutation in 37% of patients’ tumours." (PMID 35574322, 2022). "In addition, up-regulation of EGFR expression was found in BRAF inhibitor resistant cell lines and resistant tumor biopsies." (PMID 35912223, 2022).
tumor (continued). "We show that, counter-intuitively, the optimal protocol in combination therapy of BRAF/MEK inhibitors with a hypothetical drug targeting cell states that develop later during the tumor response to kinase inhibitors, is to treat first with this hypothetical drug." (PMID 35494017, 2022). "In MSI-high cases, the use of NSAIDs was associated with over a 70% risk reduction in KRAS- or BRAF-WT tumours, but no reductions were found in KRAS- or BRAF-mutant cases." (PMID 35764787, 2022). "Abundant evidence indicates that inactivation of BRAF could cause cancer cell apoptosis, thus demonstrating the necessity of mutant BRAF in tumor cells." (PMID 36619616, 2022). "Overexpression of HER2 and HER3 may provide a RAIR-DTC tumor escape mechanism for BRAF mutant cells treated with the BRAF inhibitor vemurafenib." (PMID 36157447, 2022). "Finally, taking for granted the prognostic significance of tumor mutational status, KRAS and BRAF mutations were correlated with TLR9—T1237C, TLR9—T1486C polymorphisms, and TLR9—T1486C, respectively." (PMID 36139567, 2022). "A lot of neoplasms, both hematological and nonhematopoietic, have been shown to carry the BRAF V600 E point mutation, which turns on the BRAF pre-oncogene." (PMID 36721560, 2022). "In addition, combined treatment with BRAF/MEK inhibitors can provide rapid symptomatic relief in patients with a high tumor burden and symptomatic disease at baseline." (PMID 36428582, 2022). "Recently, a homozygous deletion of CDKN2A/B, corresponding to the loss of 9q21.3, was found as a rather distinctive molecular feature of PXA, regardless of tumor grade or BRAF mutation." (PMID 36699536, 2022). "The prognostic effect related to TERT promoter mutations was not present when BRAF mutation occurred separately, showing that the co-existence of both mutations is determinant for tumor aggressiveness." (PMID 36605433, 2022). "The deletion of PTEN in mutant BRAF nevi has also been reported to drive tumor development in vivo." (PMID 35267541, 2022). "Furthermore, the clinical rationale of molecular tumor characterization regarding BRAF, KIT or NRAS, as well as the therapeutic value of immunotherapy, chemotherapy and targeted therapy, has not yet been deeply explored and clearly established in MM." (PMID 35052829, 2022). "The tumor-specific DNA markers including point mutations in EGFR or BRAF genes, rearrangements involving ALK or ROS1 genes and fusions of NTRK1/2/3 genes along with tumor mutation burden (TMB) and PDL-1 RNA expression serve as guides in proper therapy selection." (PMID 35837614, 2022). "The BRAF expression was statistically significant with tumor type (p=0.008)." (PMID 35646190, 2022). "BRAF V600E has prognostic value as it correlates with tumor progression." (PMID 35646190, 2022). "However, right-sided tumours, tumours of the MSI subtype and BRAF-mutated tumours are known to be more frequent in older women." (PMID 36497419, 2022). "BRAFi exert their anti-tumor effects by targeting the monomeric form of V600-mutant BRAF." (PMID 35513054, 2022). "BRAF-targeted therapy alone provides limited durable disease control but creates favorable effects in the tumor microenvironment; these effects include increased antigen and HLA expression, increased T-cell infiltrate, reduced immunosuppressive cytokines, and improved T-cell function." (PMID 36686803, 2022). "Based on the understanding that ctDNA could be used as a sensitive biomarker of response and progression on therapy, the DyNAMIc trial (circulating tumour DNA guided adaptive BRAF and MEK inhibitor therapy) has been developed." (PMID 35133615, 2022). "However, after long-term application of BRAF inhibitor, residual tumor unresponsive to treatment has been reported." (PMID 35055392, 2022).
tumor (continued). "Regardless, in our patient, BRAF V600E mutation is not present in her tumor, and therefore, the probability of response to targeted therapy is very low." (PMID 36703629, 2022). "In four cases, however, LP detected no PD in RAS and BRAF wild‐type tumor; in one case, LP detected no PD, although the primary tumor was RAS mutated." (PMID 34873826, 2022). "For example, in a retrospective cohort study, central LN metastases were found to be associated with tumor size (> 5 mm) but not with the BRAF mutation." (PMID 36313748, 2022). "The BRAF V595E variant was absent and in c-kit, a single nucleotide polymorphism was found in 16/70 tumours (23%)." (PMID 35202309, 2022). "Evidence already exists showing that women whose tumours contain a KRAS or BRAF mutation have a better outcome than those whose tumours do not carry these MAPK pathway-activating mutations." (PMID 35123694, 2022). "Moreover, our study demonstrated that BRAF V600E constitutively activates mitochondrial ERK (mERK) to inhibit GSK‐3‐dependent CypD phosphorylation, thereby making BRAF V600E mutant tumour cells more resistant to mPTP opening." (PMID 35748101, 2022). "Furthermore, we will be investigating mechanisms of response and resistance against BRAF targeted therapy though comprehensive genomic profiling on tumor tissue and blood for circulating tumor DNA analysis." (PMID 36527039, 2022). "To date, the principal indications for liquid biopsy in CRC are: i) RAS and BRAF testing as substitute for tumor tissue analysis in stage IV metastatic CRC and ii) RAS mutational profiling for rechallenge in patients resistant to first line anti-EGFR therapies." (PMID 35837109, 2022). "However, these analyses should be also conducted in patients with BRAF-WT CRC to explain that these features in tumor biology are confined to BRAF-MT tumors." (PMID 35625987, 2022). "Tumor microenvironment is known to increase resistance to BRAF inhibitors." (PMID 35440004, 2022). "In addition, the pathways related to tumor metastasis were also enriched in BRAF-enriched Subtype, including the Notch signaling and focal adhesion." (PMID 36253446, 2022). "Reported risk factors for peritoneal seeding include tumor cell spillage during surgery of the primary CRC, locally advanced tumor stage (T4), lymph node metastases, right sided, mucinous or signet cell cancers, or aberrations in KRAS/BRAF signaling." (PMID 35927254, 2022). "The results of the data from this report suggested that the presence of H3 K27M mutation in tumor with no malignant feature should not automatically define the lesion as Grade 4 and that BRAF status should always be assessed." (PMID 36077798, 2022). "This, however, cannot be generalized to all BRAF-mutant tumor lineages." (PMID 36476495, 2022). "Regardless of the tumor context, the mutations are mutually exclusive and are also mutually exclusive with BRAF and NRAS mutations." (PMID 35158973, 2022). "In the analysis of all PTCs, BRAF V600E mutation alone was more frequently observed in male sex (p < 0.001), tumor size ≤ 1 cm (p < 0.001), classic PTCs (p < 0.001), no perinodal infiltrations (p = 0.005), and N1 (p = 0.009) and M0 (p < 0.001) stages." (PMID 36230856, 2022). "Our study suggests that the regulation of mPTP in BRAF V600E mutant tumours may be an important therapeutic target." (PMID 35748101, 2022). "Although our approach is particularly effective in treating tumors with the BRAFV600E mutation, it is also active in cancers without oncogenic BRAF mutations via indirectly targeting the host-derived tumor stromal compartment." (PMID 35899070, 2022).
tumor (continued). "Our study contributes novel insights into the interactions between tumor cells and infiltrating immune cells, confirming that HTR3A and NIPAL4 may be involved in BRAF-mutated PTC by interfering with immune cells." (PMID 35757399, 2022). "Subsequent identification of ALK rearrangements and several cancer‐driver events, including ROS1, NRG1, NTRK1/RET fusion, BRAF (V600E) mutation, or MET amplification/Exon14 skipping, strengthened the concept of oncogene addiction and tumor heterogeneity as a pillar of modern cancer therapeutics." (PMID 35838331, 2022). "Finally, we also explored the possible relevance of the novel molecular mechanisms described here for the treatment of mutant BRAF tumours." (PMID 35941108, 2022). "Similarly, one patient had a BRAF WT tumor in the metastatic tissue and a BRAF MT (BRAFN581H) tumor in the primary tissue." (PMID 35592200, 2022). "Remarkably, one patient who received first-line immunotherapy achieved tumor shrinkage of approximately 55%, even with the BRAF V600E mutation; the PFS was 22.4 months and the OS was not attained." (PMID 36389780, 2022). "On the other hand, PFS benefit of immunotherapy was nearly identical for patients with BRAF wild-type tumours and those with BRAF V600E tumours, although arguably, the control arm regimens were inadequate for this subpopulation and a triplet chemotherapy with bevacizumab should be more effective." (PMID 35574322, 2022). "Besides, BRAF inhibition was associated with increased infiltration of CD4+T, CD8+T cells and reduced levels of myeloid-derived suppressor cells (MDSCs), tumor-associated macrophages (TAMs)." (PMID 36531226, 2022). "The hallmark molecular feature of this tumor seems to be co-deletion of 1p/19q and the pathologic activation of the MAPK, which may occur in 80% of DLGNT, mostly KIAA1549:BRAF fusions, that were found in 66% of them." (PMID 36077798, 2022). "Thus, the epigenetically-mediated reconstruction of tumor cell expression patterns is of principal importance for the acquisition of resistance to both BRAF inhibitors and checkpoint immunotherapies." (PMID 35409020, 2022). "In the current model, it is thus evident that early tumor development, driven by mutant BRAF, does not require any additional mutations in protein-coding genes." (PMID 34379110, 2022). "On the contrary, BRAF-mutated CRC demonstrated a relative resistance to BRAFi, suggesting that responses may be tumor/histology dependent." (PMID 35272691, 2022). "Our BRAF-mutated models demonstrated the highest level of sensitivity to combined therapy of selumetinib and KRT-232 and greatest tumor reduction, especially in our PDX.008 model (which harbors an activating BRAF K601N mutation), despite introduction of a hiatus and re-challenging with treatment." (PMID 35075200, 2022). "Moreover, HMGB1 functioned as the executor of pyroptotic cell death to participate in the regulation of tumor immune microenvironment via the inhibition of mutant BRAF and MEK." (PMID 36267972, 2022). "Importantly, upregulation of GRB7 was detected in CRC tissues (from TCGA data) with KRAS mutations, BRAF mutation, and double wild-type genotypes compared to that in normal colon tissues, suggesting an intrinsic function of GRB7 in tumor tissue." (PMID 34718347, 2022). "Although tumor tissue analysis by IHC remains the gold standard for most clinical molecular analysis for targeted therapy selection (with the exception of NGS for EGFR, BRAF or NTRK gene variants), it faces several biological and technological challenges." (PMID 35714131, 2022). "Mutations in tumor suppressors FBXW7 and ATM display a higher prevalence in BRAF mutated cancers." (PMID 36079062, 2022). "BRAF V600E has a great influence on the mechanisms of tumor progression in various tissues." (PMID 35163468, 2022).
tumor (continued). "Importantly, a BRAF/MEK inhibitor-resistant but high-AXL-expressing tumor sub-population was killed by the anti-AXL ADC, while BRAF/MEK inhibition was specifically cytotoxic for the low-AXL-expressing tumor cells." (PMID 35159045, 2022). "The tumour size for patients with a negative BRAF V600E mutation was significantly larger in comparison to patients who tested positive for the mutation (3.47 cm vs 2.31 cm, respectively, P = 0.009)." (PMID 34734568, 2021). "In addition to the microsatellite status (MSS), the epithelial mesenchymal transition was checked in each tumor using the biomarkers β-catenin and E-cadherin, same as KRAS and BRAF mutations." (PMID 33671994, 2021). "All the patients with a complete response had BRAF wild-type tumor." (PMID 32542563, 2021). "In melanoma, the BRAF V600E mutation is linked to increased STAT3 activity and increased expression of IL-1, IL-10, and IL-6, which in turn influence dendritic cell activity within the tumour microenvironment." (PMID 33669775, 2021). "In this study, we first investigated AIM2 expression level in BRAF-mutant CRC tumor tissues." (PMID 33842454, 2021). "In this study we identified the tumor suppressor miR-129-5p to be induced during BRAF inhibition." (PMID 34063443, 2021). "The combination treatments of BRAF inhibitors (vemurafenib) and EGFR inhibitors, namely gefitinib, erlotinib, or cetuximab, in patients with CRC synergistically inhibited mutated BRAF V600E (BRAFV600E) tumor growth in xenograft models." (PMID 34884633, 2021). "Moreover, we confirmed the antitumor effect of AIM2 in BRAF-mutant CRC cell-derived tumor xenograft (CDX) models as well as patient-derived organoids (PDOs)." (PMID 33842454, 2021). "Establishment of CRC organoids appears to be more challenging from tumours that are characterized as MSI, BRAF mutated, poorly differentiated and/or of mucinous type, which may complicate the use as a tool for prediction." (PMID 34321074, 2021). "Therefore, treatment strategies should be based on patient-related factors (age, PS, comorbidity, and preferences) and disease-related factors (tumor aggressiveness, disease burden, presence of symptoms, RAS/BRAF mutational status, and MSI-H)." (PMID 34299337, 2021). "Through analyses of a variety of human KRAS, NRAS or BRAF mutant cell lines from different tumor entities (CRC, NSCLC, PDAC, RMS) we further showed that these principles also apply to the complex genetic backgrounds that arise during human RAS-pathway driven cancer development." (PMID 33924486, 2021). "This is a novel trial in evaluating the clinical benefits of continuing EGFR inhibition versus VEGF inhibition in treating wild-type KRAS, NRAS and BRAF V600E mCRC tumors with second-line cetuximab or bevacizumab plus chemotherapy crossover after tumor progression to first-line cetuximab regimen." (PMID 34335943, 2021). "Improving identification of NIFTP by assessment of the BRAF-RAS axis may help ensure it remains an indolent neoplasm, assist with safe de-escalation of therapy, and prevent overtreatment." (PMID 33299111, 2021). "Mutant BRAF is a prototype of the driver oncogene; its inactivation leads to cancer cell apoptosis, thereby indicating the existence of an acquired dependency of tumor cells on this mutant form of BRAF." (PMID 33474634, 2021). "The role of IS remains unclear in mCRCs and needs to be validated in a prospective trail design, ideally combined with known prognostic (BRAF, RAS), molecular makers (PD-L1 expression) and tumor mutational burden (TMB)." (PMID 33675399, 2021). "Whereas, HDAC8 knockdown inhibited BRAF resistance and decreased tumor size." (PMID 33670008, 2021). "Likewise, mutational status of RAS, BRAF, and ERBB2, as well as tumor-sidedness, are clinically relevant to guide therapy options." (PMID 34805267, 2021). "In addition, BRAF p.V600E, p.G466V, and p.L597R, as well as BRCA2 mutations, were also considered actionable based on the observations from other tumor types." (PMID 34594355, 2021).